TMEM132E (transmembrane protein 132E)
Description:
Required for normal inner ear hair cell function and hearing.
Synonyms: DFNB99
Tractability: Antibody: UniProt predicts a signal peptide or a membrane-spanning region. PROTAC: its protein half-life has been measured.
Gene: Protein-coding gene on chromosome 17 (34,579,487 to 34,639,318, forward strand). Ensembl gene ENSG00000181291.
Subcellular location: Membrane
Subcellular location (Human Protein Atlas): Golgi apparatus; Nucleoplasm; Cytosol; Nuclear bodies
Gene Ontology:
Biological process: posterior lateral line neuromast hair cell development
Cellular component: cell body; membrane
Genetic constraint (gnomAD): Loss-of-function variants: 49 observed, 71.74 expected, observed/expected ratio (o/e) 0.68, 90% interval 0.54 to 0.87. The upper end of that interval is the gene's LOEUF score, 0.87, which puts it in group 3 of 6, group 1 being the genes least tolerant of losing a copy. Missense variants: 1,332 observed, 1,382.2 expected, observed/expected ratio (o/e) 0.96, 90% interval 0.92 to 1.01. Synonymous variants: 682 observed, 629.01 expected, observed/expected ratio (o/e) 1.08, 90% interval 1.02 to 1.15.
Gene-disease validity (ClinGen):
ClinGen rates the evidence that TMEM132E causes each of these diseases.
hearing loss, autosomal recessive (autosomal recessive): Limited.
Homologues: Orthologues: chimpanzee TMEM132E (99% identical), macaque TMEM132E (98% identical), dog TMEM132E (96% identical), guinea pig TMEM132E (95% identical), rabbit TMEM132E (95% identical), mouse Tmem132e (92% identical), rat Tmem132e (92% identical), pig TMEM132E (88% identical), tropical clawed frog tmem132e (63% identical), zebrafish tmem132e (57% identical), Drosophila melanogaster dtn (27% identical), Caenorhabditis elegans tmem-132 (16% identical). Paralogues in human: TMEM132C (43% identical), TMEM132D (40% identical), TMEM132B (36% identical), TMEM132A (31% identical).
Diseases named in the same sentence as TMEM132E in open-access papers:
TMEM132E is named in the same sentence as 15 diseases in open-access papers, as found by Europe PMC text mining. Sharing a sentence is not in itself a finding about the gene and the disease. The quoted sentences say what the papers report.
hearing loss (5 papers, 2019 to 2025). "Interestingly, mutations were also observed in SLC35G4, a predicted nucleotide sugar transporter, and TMEM132E, a transmembrane protein associated with nonsyndromic hearing loss." (PMID 41488087, 2025). "TMEM132E was found to be highly expressed in murine inner hair cells, and a variant in TMEM132E was identified as the most likely cause of autosomal-recessive nonsyndromic hearing loss." (PMID 31708969, 2019). "Furthermore, it is part of a family of transmembrane proteins to which TMEM132E gene belongs, where mutations that cause DFNB99 nonsyndromic hearing loss were also described." (PMID 33260921, 2020).
panic disorder (3 papers, 2019 to 2023). An anxiety disorder characterized by multiple unexpected panic attacks with persistent concern of recurring attacks. "Genetic studies have linked TMEM132E (rs10491113) to insomnia (rs145258459) associated with cardiometabolic diseases, bipolar disorder (rs10491113), and panic disorder (rs887231, rs887230, and rs4795942)." (PMID 37686257, 2023). "Neural adhesion and immunologic functions may also be influenced by TMEM132E, which has been associated with panic disorder, while other TMEM family members have been related to high-functioning autism." (PMID 34828266, 2021). "Other members of the TMEM gene family, TMEM132E and TMEM132D genes are associated with bipolar and panic disorders, respectively, while TMEM231 is a known syndromic autism gene." (PMID 31323913, 2019). "Additionally, two other members (TMEM132E and TMEM132D) are known to be associated with bipolar and panic disorders." (PMID 31323913, 2019).
breast carcinoma (1 paper, 2020). "There was only one report of ABHD14A in cancer where it was downregulated in breast cancer with visceral organ metastasis; however, the ABHD14A and TMEM132E AS events were not fully explored." (PMID 33142748, 2020).
colorectal cancer (1 paper, 2022). A primary or metastatic malignant neoplasm that affects the colon or rectum. "In addition, these hypermethylated genes, mainly PRDM14, RALYL, ELMOD1, and TMEM132E, were validated and confirmed in colorectal cancer by using publicly available DNA methylation data." (PMID 35065650, 2022). "MeDIP-seq can be used as an optimal approach for analyzing cfDNA methylomes, and 12 probes of four differentially methylated genes identified by MeDIP-seq (PRDM14, RALYL, ELMOD1, and TMEM132E) could serve as potential biomarkers for clinical application in patients with colorectal cancer." (PMID 35065650, 2022).
lung carcinoma (1 paper, 2020). "The AS of TMEM132E had a similar effect on TMEM132E, and we suggest that this protein may function as a tumor suppressor in the development of lung cancer; however, further studies are needed to confirm our suggestion." (PMID 33142748, 2020).
microcephaly (1 paper, 2014). A congenital or acquired developmental disorder in which the circumference of the head is smaller than normal for the person's age and sex. "Variants in TMEM132E (rs4795954, MAF 13.2%) and in DPYD (rs2297595, MAF 6.1%) are common, and neither has been associated with brain development or microcephaly." (PMID 23692340, 2014).
Stroke (1 paper, 2023). Sudden impairment of blood flow to a part of the brain due to occlusion or rupture of an artery to the brain. "The association between HS6ST1, TMEM132E, RFFL, and atherothrombotic stroke is less clear." (PMID 37686257, 2023).
Vertigo (1 paper, 2022). An abnormal sensation of spinning while the body is actually stationary. "The eQTL-based TWAS identified 99 cis-regulated expression genes associated with vertigo, such as RAB3B (PTWAS = 0.017), TMEM132E (PTWAS = 0.002), and TCEA3 (PTWAS = 0.037)." (PMID 36519156, 2022).
TMEM132E also shares sentences with these, for which no sentence is quoted: autism (2 papers); tumor (2); bipolar disorder (1); cancer (1); Hearing impairment (1); insomnia (1); triple-negative breast carcinoma (1).